TREM2 (triggering receptor expressed on myeloid cells 2)
Diseases named in the same sentence as TREM2 in open-access papers (continued):
Sharing a sentence is not in itself a finding about the gene and the disease.
TREM2 also shares sentences with these, for which no sentence is quoted: Glucose intolerance (8 papers); Parkinson’s (5); breast tumor (4); liver (3); peripheral neuropathy (3); renal carcinoma (3); vascular dementia (3); cholangiocarcinoma (2); cognitive disorder (2); Dementia with Lewy body (2); encephalitis (2); endotoxemia (2); frontotemporal lobe dementia (2); Gaucher disease (2); genetic disease (2); hearing loss (2); late-onset Alzheimers disease (2); multiple system atrophy (2); prostate adenocarcinoma (2); respiratory infection (2); spinal cord injury (2); abdominal aortic aneurysm (1); Acute hepatitis (1); acute kidney injury (1); acute respiratory distress syndrome (1); alien limb syndrome (1); allergic asthma (1); amnesia (1); aortic atherosclerosis (1); arterial diseases (1).
A further 87 diseases each share a sentence with TREM2 in 1 paper.